HEATR1 (HEAT repeat containing 1)
Description:
Ribosome biogenesis factor; required for recruitment of Myc to nucleoli. Involved in nucleolar processing of pre-18S ribosomal RNA. Required for optimal pre-ribosomal RNA transcription by RNA polymerase I. Part of the small subunit (SSU) processome, first precursor of the small eukaryotic ribosomal subunit. During the assembly of the SSU processome in the nucleolus, many ribosome biogenesis factors, an RNA chaperone and ribosomal proteins associate with the nascent pre-rRNA and work in concert to generate RNA folding, modifications, rearrangements and cleavage as well as targeted degradation of pre-ribosomal RNA by the RNA exosome. Involved in neuronal-lineage cell proliferation.
Synonyms: BAP28; UTP10; FLJ10359
Tractability: Small molecule: a structure with a bound ligand is known. PROTAC: ubiquitination databases record sites on it; its protein half-life has been measured.
Gene: Protein-coding gene on chromosome 1 (236,549,005 to 236,604,516, reverse strand). Ensembl gene ENSG00000119285.
Subcellular location: Nucleus, nucleolus
Subcellular location (Human Protein Atlas): Nucleoli fibrillar center; Mitochondria
Pathways (Reactome):
Metabolism of RNA: Major pathway of rRNA processing in the nucleolus and cytosol; rRNA modification in the nucleus and cytosol
Gene Ontology:
Molecular function: protein binding; RNA binding; snoRNA binding
Biological process: neural precursor cell proliferation; positive regulation of rRNA processing; positive regulation of transcription by RNA polymerase I; protein localization to nucleolus; ribosomal small subunit biogenesis; rRNA metabolic process; maturation of SSU-rRNA; maturation of SSU-rRNA from tricistronic rRNA transcript (SSU-rRNA, 5.8S rRNA, LSU-rRNA)
Cellular component: fibrillar center; membrane; mitochondrion; nucleolus; small-subunit processome; 90S preribosome; nucleoplasm; t-UTP complex
Genetic constraint (gnomAD): Loss-of-function variants: 49 observed, 199.2 expected, observed/expected ratio (o/e) 0.25, 90% interval 0.19 to 0.31. The upper end of that interval is the gene's LOEUF score, 0.31, which puts it in group 1 of 6, group 1 being the genes least tolerant of losing a copy. Missense variants: 2,043 observed, 2,203.1 expected, observed/expected ratio (o/e) 0.93, 90% interval 0.89 to 0.96. Synonymous variants: 769 observed, 832.36 expected, observed/expected ratio (o/e) 0.92, 90% interval 0.87 to 0.98.
Homologues: Orthologues: chimpanzee HEATR1 (99% identical), macaque HEATR1 (97% identical), rabbit HEATR1 (90% identical), dog HEATR1 (90% identical), pig HEATR1 (89% identical), guinea pig HEATR1 (87% identical), rat Heatr1 (85% identical), mouse Heatr1 (84% identical), tropical clawed frog heatr1 (61% identical), zebrafish heatr1 (54% identical), Drosophila melanogaster l(2)k09022 (28% identical), Caenorhabditis elegans toe-1 (16% identical).
Diseases named in the same sentence as HEATR1 in open-access papers:
HEATR1 is named in the same sentence as 27 diseases in open-access papers, as found by Europe PMC text mining. Sharing a sentence is not in itself a finding about the gene and the disease. The quoted sentences say what the papers report.
pancreatic cancer (8 papers, 2020 to 2025). "Pancreatic cancer HEAT repeat-containing protein 1 (HEATR1) deficiency can affect pancreatic cancer chemotherapy sensitization via the upregulation of ZNF185." (PMID 37396042, 2023). "The deficiency of HEAT repeat containing 1(HEATR1) can promote pancreatic cancer proliferation and gemcitabine resistance by up-regulating NRF2 signal." (PMID 34681603, 2021). "In our previous study, we discovered that downregulation of HEATR1 in pancreatic cancer causes resistance to gemcitabine." (PMID 32565799, 2020). "Besides, the relevance of our study was confirmed in the samples of pancreatic cancer patients, and we demonstrated that HEATR1, ZNF185, and SMAD4 expression are significantly associated with the prognosis with pancreatic cancer in the patients treated with gemcitabine chemotherapy." (PMID 32565799, 2020). "This research also demonstrated that treatment of the AKT inhibitor triciribine improved the chemosensitivity of gemcitabine in HEATR1-depleted pancreatic cancer cells." (PMID 38067329, 2023). "We confirmed the chemosensitive function of ZNF185 by observing the elevation of apoptotic percentage and proliferative inhibition of pancreatic cancer cells after knocking down both HEATR1 and ZNF185 and treated with gemcitabine." (PMID 32565799, 2020). "We found that the chemoresistance pancreatic cancer to gemcitabine was much more significant after HEATR1 knockdown, and the apoptotic percentage decreased when proliferation increased dramatically on day 5 after HEATR1 was knockdown." (PMID 32565799, 2020). "Additionally, the reported link between HEATR1 depletion and chemoresistance in pancreatic cancer suggests its involvement in critical pathways like Akt and Nrf2, which are known to impact drug sensitivity." (PMID 40647532, 2025). "For example, in oral squamous cell carcinoma (OSCC), HEATR1 acts as a binding factor for the Pontin/Reptin complex, which is overexpressed in tumor cells, while in pancreatic cancer HEATR1 inhibits the activity of the Nrf2 factor that participates in the protection of cells from oxidative stress." (PMID 39465903, 2024). "After we examined the HEATR1 mRNA levels in 5 pancreatic cell lines, we firstly knocked down HEATR1 expression in the pancreatic cancer cell line PANC-1 using the RNA interference technique through the lentivirus vector (shHEATR1) and the scrambled sequence as the negative control (shCtrl)." (PMID 32565799, 2020). "Moreover, HEATR1 negatively regulates Akt and sensitize pancreatic cancer cells to chemotherapy." (PMID 32123287, 2020). "Taken together, it is the first time to reveal that HEATR1, ZNF185, and SMAD4 are correlated in the chemosensitivity of gemcitabine in pancreatic cancer." (PMID 32565799, 2020). "From the multivariate survival analysis, we observed that high TNM staging, poorer differentiation, higher staining of HEATR1, or lower staining of ZNF185 in pancreatic cancer were the independent prognostic factors of pancreatic cancer patients." (PMID 32565799, 2020). "In this study, our team aim is to discover novel functional genes correlated with HEATR1 in sensitizing pancreatic cancer cells to gemcitabine, which may help to search for a new therapeutic target and improve the efficacy of gemcitabine in the pancreatic cancer." (PMID 32565799, 2020). "HEATR1, ZNF185, and SMAD4 could affect the chemosensitivity of gemcitabine and may be the indicators of gemcitabine selection in the chemotherapy of pancreatic cancer." (PMID 32565799, 2020).
glioma (5 papers, 2014 to 2024). A benign or malignant brain and spinal cord tumor that arises from glial cells (astrocytes, oligodendrocytes, ependymal cells). "As a glioma-associated antigen, Heatr1 can induce functional cytotoxic T lymphocytes, and as immune cells, the microglia-T cell interaction and their reciprocal signaling effect have been studied and reported in many researches." (PMID 37814314, 2023). "HEATR1 is also overexpressed in patient-derived GSCs compared to normal brain tissue or NSCs, and its expression inversely correlates with glioma patient survival." (PMID 38225354, 2024). "Interrogating TGCA, REMBRANDT and CGGA databases reveals that HEATR1 expression in glioma inversely correlates with patient survival (Fig. EV2C)." (PMID 38225354, 2024). "High HEATR1 expression correlates with poor glioma patient survival and patient-derived glioblastoma stem cells rely on HEATR1 for enhanced ribogenesis and tumourigenic potential." (PMID 38225354, 2024). "Database analysis also indicates HEATR1 upregulation in GBM compared to grade II gliomas." (PMID 38225354, 2024). "In support, HEATR1 expression in glioma negatively correlates with patient survival but a positive correlation was also found in pancreatic ductal adenocarcinoma where it is thought to aid sensitization to chemotherapeutic gemcitabine via AKT signalling inactivation." (PMID 38225354, 2024). "In addition to the secretion of tumor-damaging cytokines such as IFN-γ, CTLs can recognize antigens such as HEAT repeat-containing protein 1 (HEATR1) expressed by glioma cells via human leukocyte antigen (HLA)-A2 [or major histocompatibility complex class 1 in animals] and trigger cell lysis." (PMID 34211978, 2021). "We demonstrate that HEATR1 localises predominantly in the nucleoli of GSCs, GBM and lower grade glioma tissue (Fig. EV4A–J)." (PMID 38225354, 2024). "However, the expression level of HEATR1 proteins did not appear to be correlated with glioma grade (data not shown)." (PMID 25126583, 2014).
hepatocellular carcinoma (2 papers, 2024). A malignant tumor that arises from hepatocytes. "Of note, while our work was in revision, HEATR1 was published to be upregulated by the Target of Rapamycin Complex 1 signalling and promote hepatocellular carcinoma (HCC) development." (PMID 38225354, 2024). "In the case of hepatocellular carcinoma (HCC) HEATR1 is up‐regulated through the IGF1‐mTORC1‐SP1 axis." (PMID 39465903, 2024).
pancreatic ductal adenocarcinoma (2 papers, 2019 to 2024). An infiltrating adenocarcinoma that arises from the epithelial cells of the pancreas. "Lastly, correlation of HEATR1 with shorter overall survival has been shown in pancreatic ductal adenocarcinoma." (PMID 30704450, 2019).
brain cancer (1 paper, 2024). A primary or metastatic malignant neoplasm affecting the brain. "This study explored the transition from tumour-initiating cells (TIC) to brain cancer cells and discovered that increased OxPhos activity upregulates ribogenesis, mediated by the interaction between HEAT-Repeat Containing 1 (HEATR1) and Myc." (PMID 39682725, 2024).
brain tumour (1 paper, 2024). "Transcriptome reshaping of single brain tumour initiating cells reveals metabolic and proteostatic changes including a HEATR1-dependent ribogenesis boost." (PMID 38225354, 2024). "It is thus interesting to postulate that HEATR1 may also be a MYC target during brain tumour development." (PMID 38225354, 2024). "HEATR1’s binding and modulation of MYC nucleolar localisation and its requirement for rRNA generation lead us to propose it as a molecular mechanism underlying ribogenesis reprogramming of brain TICs, shedding new light on the transition into brain tumour growth." (PMID 38225354, 2024). "HEATR1 interacts with MYC, promotes its nucleolar localization, and enhances overgrowth of brain tumour initiating cells." (PMID 38225354, 2024). "We further show that HEATR1 binds the master ribogenesis and cell growth regulator MYC and promotes its localisation to ribogenesis sites, suggesting a mode of action to enhance ribogenesis during early TIC development stimulating the transition into brain tumour growth." (PMID 38225354, 2024).
breast carcinoma (1 paper, 2020). "Mutant plectin (PLEC), marker Of Proliferation Ki-67 (MKI67), HEAT Repeat Containing 1 (HEATR1) and AHNAK nucleoprotein (AHNAK) were detected in three of the four breast cancer cell lines." (PMID 33274046, 2020).
clear cell renal cell carcinoma (1 paper, 2025). "This study investigated the expression of HEAT repeat-containing protein 1 (HEATR1) and solute carrier family 27 member 2 (SLC27A2) in clear cell renal cell carcinoma (ccRCC)." (PMID 40647532, 2025).
gastric cancer (1 paper, 2024). A primary or metastatic malignant neoplasm involving the stomach.
leukemia (1 paper, 2014). A malignant (clonal) hematologic disorder, involving hematopoietic stem cells and characterized by the presence of primitive or atypical myeloid or lymphoid cells in the bone marrow and the blood. "A recent study indicated that HEATR1 is an ideal minor histocompatibility antigen that is expressed by leukemia stem cells." (PMID 25126583, 2014).
lymphoma (1 paper, 2019). A malignant (clonal) proliferation of B- lymphocytes or T- lymphocytes which involves the lymph nodes, bone marrow and/or extranodal sites. "Mutations within ELF2 and HEATR1 were identified in T-cell leukemia/lymphoma patients." (PMID 31046777, 2019).
malignant glioma (1 paper, 2014). A grade III or grade IV glioma arising from the central nervous system. "Interestingly, HEATR1-specific CTLs are only detectable in PBMC derived from patients with malignant gliomas but not in PBMC from healthy donors." (PMID 25126583, 2014).
osteosarcoma (1 paper, 2024). A usually aggressive malignant bone-forming mesenchymal neoplasm, predominantly affecting adolescents and young adults. "HEATR1 has been proposed to be required for ribogenesis in osteosarcoma U2OS cells and during zebrafish CNS development." (PMID 38225354, 2024).
cancer (6 papers, 2018 to 2025). A tumor composed of atypical neoplastic, often pleomorphic cells that invade other tissues. "While HEATR1 has been previously implicated in other cancers, its role in ccRCC remains to be fully elucidated." (PMID 40647532, 2025). "While our study is the first to explore HEATR1 in ccRCC, its role in other cancers has been investigated." (PMID 40647532, 2025). "In line with our findings, HEATR1 is upregulated in various cancer types, where it fuels tumor growth by enhancing ribosome production." (PMID 40647532, 2025). "In summary, HEATR1 is crucial for ribogenesis and has been increasingly implicated in the development of different cancers but its modes of action may vary not only between tumour types but also between transition into tumourigenesis and progression of established cancers." (PMID 38225354, 2024). "HEATR1 showed mainly low expression of 80% (64/80) in cancer and high expression of 65% (52/80) in normal pancreas." (PMID 32565799, 2020). "While its exact role in cancer remains unclear, HEATR1 exhibits high expression in glioblastoma tissues and cytotoxic T lymphocytes of glioma patients." (PMID 40647532, 2025). "Furthermore, HEATR1 might be involved in the heightened ribosome biogenesis that is characteristic of cancer cell proliferation." (PMID 40647532, 2025). "High HEATR1 and low SLC27A2 expression correlated with cancer progression, relapse, and overall survival in patients with high-grade ccRCC." (PMID 40647532, 2025). "The χ2 test showed significant differences in the expression of HEATR1 (χ2 = 37.143, P < 0.001), ZNF185 (χ2 = 20.077, P < 0.001), and SMAD4 (χ2 = 23.309, P < 0.001) between the cancer and the normal pancreas." (PMID 32565799, 2020). "For instance, in a previous study, endogenous HEATR1 levels were significantly higher in human cancer cell lines than in primary non-transformed cells." (PMID 40647532, 2025).
tumor (6 papers, 2014 to 2025). "We conclude that HEATR1 is required in GSCs for their tumourigenic capacity and proliferation, functions also observed in vivo in brat-deficient tumours." (PMID 38225354, 2024). "Our results demonstrate that brat-deficient brain TICs boost ribogenesis ahead of tumour growth in a fashion dependent on high HEATR1 expression." (PMID 38225354, 2024). "At late stages, HEATR1 depletion results in dramatically reduced tumours, however, it also decreases proliferation of control NSC lineages highlighting its requirement for normal brain development." (PMID 38225354, 2024). "HEATR1 was reported in one previous study to be overexpressed in GBM compared to non-tumour brain tissues but its role in brain tumourigenesis is unknown." (PMID 38225354, 2024). "Expression studies confirmed high HEATR1 levels in tumor tissues." (PMID 34572265, 2021). "This is consistent with a report identifying HEATR1, as well as MYC (see discussion below), as the highest scoring genes among a group of 68 ribogenesis-associated factors screened for ability to promote rRNA synthesis in a normal (non-tumour) breast cell line." (PMID 38225354, 2024). "Finally, we examined the effect of HEATR1 inhibition in brat tumours at late stages (93 h ALH)." (PMID 38225354, 2024). "In addition, we identify several HEATR1-derived T-cell epitopes in tumor carrier patients." (PMID 25126583, 2014). "The analysis showed that HEATR1 was significantly increased, while SLC27A2 was significantly decreased in tumor samples compared to normal tissue." (PMID 40647532, 2025). "IHC analysis in an independent cohort of ccRCC patients, including those with high-grade disease, demonstrated that both HEATR1 and SLC27A2 are expressed in tumor tissues." (PMID 40647532, 2025). "HEATR1 was expressed in the cytoplasm and nucleus, while SLC27A2 was expressed in the cell membrane of the tumor cells." (PMID 40647532, 2025). "Endoribonuclease-prepared small interfering RNAs (esiRNA) and lentivirus-delivered short hairpin RNA (shRNA) against HEATR1 knock it down efficiently in GBM (U87MG, U251MG) and GSCs (GSC-5 and GSC-8) derived from independent tumours." (PMID 38225354, 2024). "We next analysed HEATR1 inhibition at 48 h ALH, a developmental stage when brat TICs started to overproliferate to form a tumour and will grow indefinitely as demonstrated via serially transplant paradigms." (PMID 38225354, 2024). "High HEATR1 levels are required for an increase in ribogenesis promoting TIC development and transition into tumour growth." (PMID 38225354, 2024). "Second, tumor induced microinflammation may result in the increase of permeability of blood-brain barrier and thereby help CTL to access and recognize the presented HEATR1-derived peptide on tumor cells." (PMID 25126583, 2014).
HEATR1 also shares sentences with these, for which no sentence is quoted: Burkitt lymphoma (1 paper); Cirrhosis (1); epilepsy (1); glioblastoma (1); infection (1); migraine (1); non-small cell lung carcinoma (1); oral carcinoma (1); oral squamous cell carcinoma (1); primary open angle glaucoma (1); Sepsis (1); T-cell leukemia (1).